MAVS (mitochondrial antiviral signaling protein)
Diseases named in the same sentence as MAVS in open-access papers (continued):
Sharing a sentence is not in itself a finding about the gene and the disease.
infection (continued). "Although the data thus far indicate that Mpro is likely responsible for the cleavage of MAVS during infection, we also investigated some cellular processes that could lead to the cleavage or degradation of MAVS." (PMID 38400032, 2024). "Overall, this suggests that cleavage of MAVS specifically occurs upon infection with MERS-CoV." (PMID 38400032, 2024). "After infection, the expression of MAVS, IRF7, STING, NF-κB, MAD5, LGP2, IFN-α and IFN-β was upregulated compared with that in the control group, regardless of whether IFITM3 was overexpressed or inhibited." (PMID 38543696, 2024). "Moreover, compared to uninfected controls, the proximity of MAVS–Mfn1 and MAVS–Mfn2 was notably decreased during infection." (PMID 39338909, 2024). "Together with the high IFNβ response by YFV-17D infected cells that display a fragmented mitochondrial phenotype, these data indicate that MAVS-dependent expression of IFNβ in response to infection with these hepatotropic flaviviruses is divorced from canonical mitochondrial morphology dynamics." (PMID 39282299, 2024). "We observed using confocal microscopy and co-immunoprecipitation assays that NOD2 interacts with the effector protein MAVS (mitochondrial antiviral signaling protein), an adaptor protein promoting antiviral activity, this occurring mainly at 12 h into the infection." (PMID 38668261, 2024). "As the infection in Huh7 cells progressed, the abundance of full-length MAVS decreased, which coincided with the appearance of two additional bands of about 20 and 35 kDa that were recognized by a MAVS-specific antibody." (PMID 38400032, 2024). "Our study indicated an increased colocalization of MAVS with Mfn1/2 during infection only in cells exhibiting an unaltered or elongated mitochondrial network, which could imply enhanced interactions between these proteins." (PMID 39338909, 2024). "For example, 48 h after infection, the transcription levels of OASL, Mx, MDA5, and MAVS were upregulated in the FAdV-4 GY single-infected group (group A) and the group subjected first to FAdV-4 GY infection with aHEV-YT and then infection with aHEV-YT (group C) after culturing with LMH cells." (PMID 37896849, 2023). "However, during infection, a range of factors that target MAVS to affect the control of inflammation by IFN-Is." (PMID 38124132, 2023). "Although rSA11/WaVP3 possesses a functional NSP1, it did not cause significant MAVS depletion even late in infection (12 h p.i.), confirming that NSP1 does not contribute to MAVS degradation." (PMID 37905816, 2023). "This increase in IFNβ expression could be explained by the observed infection-induced increases in the expression of MAVS and IRF3, which were reported to be involved in IFNβ production." (PMID 36754974, 2023). "In the future, mice infected with RVFVmiR-122 could be euthanized at 12 h or 18 h to rigorously examine the innate immune response involving RIG-I and MAVS at earlier times post-infection." (PMID 37695055, 2023). "After infection with Sendai virus or stimulation with poly (I:C) or lipopolysaccharides (LPS), SER5 internalizes into the mitochondria membrane and associates with the mitochondrial membrane protein MAVS (mitochondrial antiviral signaling protein)." (PMID 35333966, 2023). "However, our results show that protein levels of ISGs such as PKR, RIG-I, MDA5 and MAVS increased at later infection times in G3BP1 KD cells." (PMID 36851680, 2023). "Moreover, the HCV NS3–4A protease also inactivates MAVS during infection to reduce antiviral signaling and recognition of the viral RNA." (PMID 35215884, 2022). "However, induction of IFN-β mRNA expression was drastically reduced in both RIG-I and MDA5 knockout cells and even more profoundly reduced in MAVS knockout cells up to 36 to 48 h post infection." (PMID 35061864, 2022).
infection (continued). "Whether other cellular factors transduce signals to alter immune gene expression, either by shuttling to mitochondria during infection or as permanent residents at the organelle like MAVS anchored to the OMM, is an area of interest." (PMID 35073751, 2022). "Roles of RIG-I, PKR, and MAVS in sensing of HMPV mutants during infection of A549 cells." (PMID 35975999, 2022). "In DENV-ADE infection, cross-reactive antibodies mediate infection by inducing autophagy related proteins, and then suppress the innate immunity mediated by the mitochondria antiviral protein (MAVS)." (PMID 35918744, 2022). "Upon infection MAVS promotes NLRP3 inflammasome activation, which influences immune responses." (PMID 36300112, 2022). "We found that SeV infection could induce MAVS aggregation in macrophages, while PRMT9 deficiency greatly increased the formation of MAVS aggregates in Prmt9CKO macrophages after infection." (PMID 36028484, 2022). "To determine whether aMPV/C infection can catalyze polyubiquitin chain formation on MAVS, we conducted ubiquitination assays in Vero cells." (PMID 34696420, 2021). "In contrast, both MAVS and DAI/Zbp1-deficiency increased the IFN-I response upon MVA-infection." (PMID 34711816, 2021). "Moreover, the NS1 and N proteins of respiratory syncytial virus attenuate the production of type I IFNs during infection by inhibiting the MAVS/RIG-I interaction and by localizing MAVS in inclusion bodies, respectively." (PMID 34782737, 2021). "Indeed, there were a little induction of IFN-α and IFN-β production in MAVS KO BMDC after first round of infection with reovirus or VSV." (PMID 33976210, 2021). "Infection with complement-opsonized HIV-1 mediates higher MAVS aggregation." (PMID 34634939, 2021). "AMPV/C infection induced polyubiquitin chains formation and MAVS polyubiquitination." (PMID 34696420, 2021). "The densitometry ratios of MAVS to β-actin bands decreased after 24 h in the virus-infected cells, it was much lower than that in the mock-infected cells from 48 h post-infection (hpi) onward (p < 0.01), indicating that aMPV/C infection induced the reduction in MAVS." (PMID 34696420, 2021). "In addition, RLR, which recognize invasive viral RNA produced during infection and, through induction of mitochondrial antiviral signaling (MAVS) molecule, can also induce type I IFN production." (PMID 34829979, 2021). "In addition, ATG7 deficiency attenuated virus-induced degradation of MAVS, and reconstitution of ATG7 in ATG7-/- cells restored the degradation of MAVS following SZ19-ΔF2 infection." (PMID 33577621, 2021). "However, the relationship between glucose metabolism and RLR signaling in epithelial cells at later time point in infection, notably in cells that with ubiquitous expression of MAVS, should be further evaluated." (PMID 33603735, 2020). "Afterwards, to known whether MAVS can affect cell proliferation and viability upon SCRV infection, we used MAVS-specific siRNA for further experiments." (PMID 32678830, 2020). "Thus far, we have demonstrated O-GlcNAcylation of the MAVS 249–257 serine-rich region results in down-regulated RLR signaling infection with SeV." (PMID 33603735, 2020). "RLR-mediated inhibition of protein translation during infection with RNA viruses is thought to occur independently of MAVS and instead may be regulated by the innate signaling adaptor STING." (PMID 33104760, 2020). "The enhanced protein level of MAVS was detected on day 1 and day 33 of the infection." (PMID 32121148, 2020). "In contrast, knockdown of MARL reduced MAVS expression upon SCRV infection." (PMID 32678830, 2020). "Although the present work centered on the antibody response relevant for the control of primary infection, we also analyzed the impact of MAVS on the IgG response to WNV, particularly since we noted enlarged GC Tfh cell and GC B cell compartments in MAVSKO mice early in the response." (PMID 33104760, 2020).
infection (continued). "As previously observed, the loss of cGAS (Fig EV5B) or MAVS (Fig EV5C) had no impact on HIV‐1 infectivity suggesting sensing does not contribute to the inhibitory effect of PF74 in these single round infections." (PMID 32852081, 2020). "In addition to its suppressing role on mRNA translation, PKR recognizes the HCV internal ribosome entry site (IRES) and contributes to an antiviral response at early stages of infection by interacting with MAVS and triggering ISG expression." (PMID 33613561, 2020). "Alternatively, MAVS signaling could be necessary during the re-activation of memory T cell in the lungs during RSV secondary infection." (PMID 33123150, 2020). "Given that MDA5 and MAVS are key players in the innate antiviral response, we analyzed their gene expression and identified a significant increase of these genes at day 5 after infection." (PMID 33490061, 2020). "A distinct MAVS cleavage product was observed upon infection with EMCV-Lpro." (PMID 32667958, 2020). "Moreover, RT-qPCR analysis also found similar expression levels of several interferon response pathway genes including type I IFN, RIG-I, and MAVS in the lung tissues after infection with either the wild-type or mutant IAV-PR8." (PMID 33281788, 2020). "To confirm whether fish MAVS is required for the induction of type I IFN and inflammatory cytokines upon SCRV infection, we silenced MAVS and examined the expression patterns of indicated genes." (PMID 32678830, 2020). "However, normal clearance of the infection is achieved by day 9, further emphasizing the importance of MAVS in the early control of RSV replication." (PMID 32290326, 2020). "Furthermore, we observed that in vitro infection of peripheral blood mononuclear cells (PBMCs) from healthy donors with the MAVS minor genotype resulted in lower levels of HIV-1 replication." (PMID 32708557, 2020). "Here, we report that transcription of OGT is dramatically decreased at early time points after infection with an RNA virus; this contributes to the depletion of the O-GlcNAcylation of MAVS at later time points after infection, which serves to promote an innate immune response." (PMID 33603735, 2020). "MAVS-/- mice survived infection from the non-pathogenic WNV-Madagascar (MAD) strain, with limited signs of disease." (PMID 31242236, 2019). "Loss of both RIG-I and MDA5 phenocopied mice lacking MAVS, as all mice succumbed to infection within 8 days after viral challenge." (PMID 31409781, 2019). "Although RIG-I predominantly recognizes RNA viruses, the RIG-I/Mitochondrial antiviral-signaling protein (MAVS) pathway is also activated during infection with several DNA viruses, including herpes simplex virus (HSV-1), Epstein-Barr virus, and Kaposi's sarcoma-associated herpesvirus." (PMID 32063900, 2019). "Interestingly, we observed a significant increase in the levels of nAbs in MAVS-/- mice at day 7 post-infection (p.i.), at a time point were nAbs were mostly undetected in WNV-MAD infected WT mice." (PMID 31242236, 2019). "In the absence of MAVS, mice die more rapidly after infection with the pathogenic WNV-Texas (TX) strain, but also produce elevated WNV-specific IgG concomitant with increased viral burden." (PMID 31242236, 2019). "Our results are consistent with a recent study showing that MAVS-/- mice that survived a primary infection of WNV with a nonstructural protein mutation (NS4B-P38G) were all protected from a lethal WNV challenge." (PMID 31242236, 2019). "In order to study the long-term antibody responses during WNV infection in the absence of MAVS, we first determined that MAVS-deficient mice can survive a non-pathogenic WNV-MAD infection." (PMID 31242236, 2019). "The infection of miRNA-transfected Dgcr8-/- cells with TMEV resulted in an increase in both susceptibility and viral replication for miR-125a-5p, miR-125b-5p and miR-673–5p, which correlated with the ability of these miRNAs to downregulate MAVS protein levels." (PMID 31012846, 2019).
infection (continued). "The infection efficiency was comparable between the isogenic cell lines, as evidenced by green fluorescent protein (GFP) expression encoded by BAC16, albeit there was slightly less expression in the MAVS KO cells." (PMID 29746593, 2018). "In support of this, it has been demonstrated that infection of cell lines with Sendai virus or treatment with p(I:C) resulted in elongation and/or fusion of mitochondria and stimulation of signaling downstream from MAVS." (PMID 29509510, 2018). "Involvement of STING in transmitting RIG-I signaling might be mediated by the formation of the RIG-I/MAVS/STING complex upon intracellular pathogen infection." (PMID 30233599, 2018). "Additionally, it is possible for SLC15A3 to use its transporter function to regulate peroxisome conditions during infection, then indirectly affecting MAVS- and STING-mediated signal transduction." (PMID 30069489, 2018). "Later in the infection we suggest that increased viperin expression, which peaks at between 6 and 8 hours after stimulation, overwhelms the sequestration mediated by its interaction with MAVS." (PMID 28207838, 2017). "Importantly, the interaction between MAPL and MAVS is decreased upon recruitment of RIG-I:dsRNA, since we observe a reciprocal interaction between RIG-I and MAVS upon infection." (PMID 28273895, 2017). "HSV-1 could activate the MAVS-Pex signaling pathway at a low multiplicity of infection (MOI), while infection at a high MOI dampens MAVS-Pex induced immediately early ISGs production." (PMID 28222744, 2017). "MAVS proteolysis has been observed during infection by poliovirus, CVB3, EV71, HRV1a, or HAV." (PMID 27999393, 2016). "In PRRSV-infected cells, the decrease of MAVS mRNA and protein became evident at D3 post-infection." (PMID 27997564, 2016). "Thus, the apparent incomplete MAVS cleavage as detected by Western blot probably reflects incomplete infection of the used Huh7 cell cultures with uncleaved MAVS being produced by non-infected cells." (PMID 26588843, 2015). "We therefore explored whether the structured SINE RNAs might serve as the MAVS activation signal to stimulate IKKβ during MHV68 infection." (PMID 26584434, 2015). "Graef and colleagues hypothesized that the reduced PB2-induced suppression of MAVS-mediated signal transduction upon infection with avian influenza viruses in comparison to human subtypes might play a role in HPAIV-induced dysregulation of cytokine expression." (PMID 26024522, 2015). "Thus, MAVS is universally targeted by the RV strains, during the early steps of infection to escape IFN induced antiviral signaling." (PMID 24643253, 2014). "Immunoblotting revealed degradation of MAVS protein after infection in a time dependent manner." (PMID 24643253, 2014). "Our study shows degradation of MAVS during infection in a RV strain independent fashion." (PMID 24643253, 2014). "However, HCV has evolved to disarm both mechanisms by NS3/4A-mediated cleavage of the essential adaptor proteins, TRIF (Toll/interleukin receptor domain-containing adapter-inducing interferon), and MAVS, once the infection is established in hepatocytes." (PMID 25111807, 2014). "Both synthetic ssRNA and ssRNA viral genomes activated IRF-3 in a NOD2- and MAVS-dependent manner, and infection with RSV resulted in increased NOD2 expression, leading to IFN production within 2 h p.i., whereas other PRRs (e.g., RIG-I) activate the IRF-3-IFN pathway during a later infection period." (PMID 24244872, 2013). "As in A549 cells, mitochondrial MAVS protein levels were decreased in response to rhMPV-ΔG infection, compared to WT, likely reflecting enhanced degradation, which has been recently shown to be required to activate downstream signaling leading to type I IFN production." (PMID 23626834, 2013).
infection (continued). "Upon infection of E. coli cells coexpressing the lambda cI repressor with either MAVS or TRIF cleavage site and a CHV NS3/4A construct, lambda phage replicated up to 2,000-fold more efficiently than in cells expressing a CHV protease variant that included a substitution in catalytic residue S139." (PMID 22870331, 2012). "Collectively, our evidence supports the hypothesis that RSV NS1 interferes with the antiviral signaling pathway by binding to the mitochondrial protein MAVS during early infection and disrupting the MAVS/RIG-I interaction that is necessary for signaling." (PMID 22383950, 2012). "Next, we tested whether resistance to cleavage by the HCV protease allows MAVS to restrict HCV replication with greater efficiency during an infection." (PMID 22427742, 2012). "We previously reported that γHV68 activates the MAVS-IKKβ pathway to promote viral lytic infection." (PMID 22110409, 2011). "While DDX50 has been described to act as a co‐factor for c‐Jun‐activated transcription, the localization of DDX50 remains unclear, with one study showing DDX50 in the cytoplasm functioning upstream of MAVS and another showing retainment in the cytoplasm following infection." (PMID 39620586, 2025). "Moreover, EIAV (EIAVDLV34) infection could inhibit the activation of the MAVS-dependent IFN-β pathway, which is induced by poly I:C, in eMDMs." (PMID 39665545, 2025). "This made us wonder whether MAVS changes localization upon infection." (PMID 38400032, 2024). "Notably, knockout of DDX11 decreased the interaction among RIG-I and MAVS upon infection with SeV." (PMID 39470258, 2024). "However, it was observed that CCCP treatment could partially decrease the level of MAVS in L929 cells at the late stages of infection (18 and/or 24 hpi)." (PMID 39338909, 2024). "To distinguish whether the cleavage of MAVS during infection was triggered by the virus or was part of a cellular negative feedback mechanism, we inhibited the proteasome and the autophagy machinery during infection." (PMID 38400032, 2024). "Overall, the ability of pantethine to reduce the infection-induced increases in MAVS, IRF3 and STING expression could explain the antiviral and anti-inflammatory effects of pantethine, which significantly inhibited IFNβ, TNFα and IL6 expression in infected Calu-3a cells." (PMID 36754974, 2023). "The interactions between those viral proteins and components of the MAVS cascade could condition the activity of MAVS in different pathways during the course of the infection, facilitating the evasion of the virus from the innate immune response and favoring its pathogenicity." (PMID 36876111, 2023). "Moreover, VP3, as a viral capping enzyme and as a PDE antagonist of the OAS-RNase L pathway, may be directed to substrates other than MAVS, again reducing its effective concentration at early times of infection." (PMID 37905816, 2023). "However, the interaction mechanism between avian metapneumovirus subgroup C (aMPV/C) infection and MAVS remains unclear." (PMID 34696420, 2021). "Likewise, MAVS is cleaved followed by infection with the Avian infectious bronchitis virus." (PMID 33807534, 2021). "Results from endogenous immunoprecipitation assays suggested that RNF115 was constitutively associated with MAVS without infection, and VSV infection or transfection of poly(I:C) impaired their associations in MLFs or bone marrow-derived dendritic cells (BMDCs)." (PMID 33139700, 2020). "Further, development of agonists for the RIG-I/MAVS pathways can be used synergistically with antiviral compounds to restrict the replication of viruses at the initial stage and offer prophylactic solution to prevent such deadly outbreaks and rapid spread of RNA-virus induced infection." (PMID 32983015, 2020). "Similarly, MAVS-/- mice experience elevated levels of inflammation following WNV-TX infection." (PMID 31242236, 2019).